MIR4298 (microRNA 4298)
Synonyms: hsa-mir-4298
Gene: MicroRNA gene on chromosome 11 (1,859,464 to 1,859,536, reverse strand). Ensembl gene ENSG00000264493.
Homologues: Orthologues: chimpanzee MIR4298 (100% identical).